H19 (H19 imprinted maternally expressed transcript)
Diseases named in the same sentence as H19 in open-access papers (continued):
Sharing a sentence is not in itself a finding about the gene and the disease.
atherosclerosis (continued). "Basic studies have also shown that H19 promotes atherosclerosis progression by promoting excessive vascular endothelial cell proliferation, inhibiting adipocyte differentiation, and inducing lipid metabolism disorders." (PMID 39432244, 2024). "H19 was the primary target lncRNA molecule of METTL3‐mediated m6A modification in the pathogenesis of atherosclerosis." (PMID 39432244, 2024). "Plaques of varying degrees were observed in the aortas of mice in the atherosclerosis, atherosclerosis+siNC+vector, atherosclerosis+si‐METTL3+vector, and atherosclerosis+si‐METTL3+H19 groups, and they were distributed across various sites." (PMID 39432244, 2024). "The level of some lncRNAs, such as CASC11, H19, TUG1, and MIAT, can be analysed in serum samples as potential diagnostic markers for atherosclerosis." (PMID 39273193, 2024). "RT‐qPCR of mouse aorta tissues showed that compared with the Control group, the H19 expression level in the aortas of mice in the atherosclerosis group was significantly increased (p < .05)." (PMID 39432244, 2024). "LncRNA H19 is well-known in tumorigenesis as a tumor suppressor, and recently, the role of H19 in other pathologies has been noticed, including atherosclerosis, osteoporosis, fibrosis, and ischemic stroke." (PMID 37508808, 2023). "H19 plays a crucial role in metabolic disorders by suppressing lipid metabolism and increasing their accumulation, contributing to the progression of atherosclerosis." (PMID 37568514, 2023). "LncRNA H19 is shown to play two roles, both protecting and inducing atherosclerosis at different times during the formation and development of that disease." (PMID 37762106, 2023). "It is suggested that H19 drives the atherosclerosis phenotype in ox-LDL-treated Raw264.7 cells by promoting lipid dysregulation and inflammatory response by targeting miR-130b." (PMID 35946958, 2022). "H19 has been reported to be up-regulated in the serum and the coronary artery plaque of patients with atherosclerosis." (PMID 35946958, 2022). "For example, lncRNA H19 is upregulated during the progression of atherosclerosis via the regulation of the MAPK and NF-κB signaling pathways." (PMID 35890121, 2022). "Another study proposes that H19 induces atherosclerosis by inhibiting apoptosis of VSMCs, which promotes foam cell formation and neointimal growth." (PMID 35946958, 2022). "This is in line with other studies on H19 in atherosclerosis and aneurysm where H19 induces VSMC proliferation." (PMID 35946958, 2022). "The abnormally expressed long non-coding RNA (lncRNA) H19 has a crucial function in the development and progression of cardiovascular disease; however, its role in atherosclerosis is yet to be known." (PMID 34820432, 2021). "These in vivo findings collectively illustrate that lncRNA H19 serves as a vital participant in the progression of atherosclerosis." (PMID 34820432, 2021). "To examine the role of lncRNA H19 and evaluate its treatment prospective in atherosclerosis, we overexpressed or knocked down lncRNA H19 in vivo using AAV in apoE−/− mice." (PMID 34820432, 2021). "A recent study showed that lncRNA H19 functions as a ceRNA to facilitate the occurrence and development of atherosclerosis." (PMID 34820432, 2021). "Subsequent overexpression of lncRNA H19 in vivo demonstrated that lncRNA H19 overexpression significantly increased the progression of atherosclerosis." (PMID 34820432, 2021). "Many investigations have demonstrated that H19 is involved in the native atherosclerosis via different mechanisms, such as cellular proliferation and apoptosis, adipocyte differentiation, inflammatory response, lipid metabolism, and regulation of angiogenesis." (PMID 33541284, 2021). "H19 also plays a specific regulatory role in diabetic retinopathy, atherosclerosis, and ankylosing spondylitis." (PMID 34288826, 2021).
atherosclerosis (continued). "The outcomes from this research illustrated that the expression of lncRNA H19 was elevated in mouse blood and aorta with lipid-loaded macrophages and atherosclerosis." (PMID 34820432, 2021). "Although lncRNA H19 facilitates the development as well as the progression of atherosclerosis, the participation of lncRNA H19 in regulating excessive lipid-induced atherosclerosis remains elusive." (PMID 34820432, 2021). "In apoE-/- mice, overexpression of H19 aggravated atherosclerosis progression; however, silencing of H19 protected against atherosclerosis." (PMID 34179148, 2021). "H19 also has proinflammatory effects in atherosclerosis by enhancing p38 expression, which is a central modulator of the MAPK and NF-κB pathways." (PMID 33193379, 2020). "Meanwhile, LncRNA H19 overexpression suppressed autophagy of vascular smooth muscle cells in atherosclerosis." (PMID 32977843, 2020). "For example, H19 appears to enhance inflammation by targeting miR-130b during the process of atherosclerosis because H19 silencing significantly mitigates TNF-α and IL-1β production in rodents." (PMID 32272875, 2020). "Both Akt activity in ECs and diabetic wound healing were enhanced by extracellular vesicle-mimetic nanovesicles carrying H19, strongly suggesting the critical role of H19 in the pathogenesis of atherosclerosis." (PMID 32241300, 2020). "While the inflammatory-mediated mechanisms are evident for H19 in atherosclerosis and neuroinflammation, the influence of H19 on inflammation during the progression of DR is not known." (PMID 31337130, 2019). "We report here, the up-regulation of H19 lncRNA in the whole blood of CAD patients and suggest a possiblerole for H19 in the atherosclerosis process and its consideration as novel biomarker for CAD." (PMID 30124004, 2019). "H19-miR130b pathway is associated with lipid metabolism and inflammation activities, also suggesting that H19 is a new target for atherosclerosis therapy." (PMID 30778327, 2019). "LncRNAs, including H19, TUG1, MIAT, and CASC11, can be detected in serum and could serve as potential diagnostic markers for atherosclerosis." (PMID 40941416, 2025). "Furthermore, m6A modification‐mediated H19 markedly promotes atherosclerosis progression by activating endothelial cell pyroptosis." (PMID 39432244, 2024). "Finally, in vivo experiments further verified the influence of METTL3‐mediated m6A modification and H19 expression in atherosclerosis." (PMID 39432244, 2024). "Therefore, METTL3 regulated the expression level of H19 by direct m6A modification in both the animal and cell models of atherosclerosis." (PMID 39432244, 2024). "Thus, the controversy surrounding the association between H19 and pyroptosis prompted us to focus on H19 in our investigation to elucidate the mechanism of atherosclerosis induction by METTL3." (PMID 39432244, 2024). "Thus, METTL3 promoted atherosclerosis progression by upregulating H19 expression levels in vivo and in vitro." (PMID 39432244, 2024). "Therefore, future studies should fully analyze various types of signaling pathways through which m6A modification‐mediated H19 aggravates atherosclerosis, leading to more comprehensive and accurate conclusions." (PMID 39432244, 2024). "LncRNA H19 is found at elevated levels in the serum of atherosclerosis patients." (PMID 38473915, 2024). "pointed out that the H19 overexpression was a key link in the occurrence of atherosclerosis." (PMID 39432244, 2024). "Therefore, binding of the reader IGF2BP2 to H19 regulated its expression in the animal and cell models of atherosclerosis." (PMID 39432244, 2024). "Additionally, clinical studies have proved that the H19 expression level in the peripheral blood of patients with atherosclerosis was obviously higher than that of ordinary subjects." (PMID 39432244, 2024). "Nevertheless, H19 also reduces vascular endothelial injury, thereby alleviating atherosclerosis." (PMID 37762106, 2023).
atherosclerosis (continued). "Statins may regulate the expression of several lncRNAs (e.g., LASER, MEG3, and H19) in patients with atherosclerosis." (PMID 37238718, 2023). "In an attempt to study the protective effect of Icariin on atherosclerosis, it was further demonstrated that enhanced expression of H19 by Icariin inhibited EndoMT in the endothelium upon ox-LDL treatment, possibly through miR-148b-3p and its target E74-like factor 5 (ELF5)." (PMID 35946958, 2022). "Thus, H19 is closely related to the formation of atherosclerosis and is an important mediator of the ox-LDL damaged vascular cells." (PMID 35345660, 2022). "Further, other scholars found that H19 is involved in the process of atherosclerosis." (PMID 35345660, 2022). "Therefore, in order to explore the effect of H19 on atherosclerosis, this study aims to elucidate the pathological mechanism of ox-LDL-induced vascular endothelial cell lesions in vitro, which would provide new therapeutic targets for atherosclerosis." (PMID 35345660, 2022). "Collectively, these findings show some discrepancies on the role of H19 in atherosclerosis." (PMID 35946958, 2022). "For instance, H19 promotes atherosclerosis by regulating MAPK and NF-kB signaling pathways." (PMID 34130625, 2021). "In this study, by comparing the aorta and blood of apoE−/− and C57BL/6 mice fed HFD, we identified that lncRNA H19 could serve an essential function in atherosclerosis." (PMID 34820432, 2021). "Compared with normal healthy people, the expression of H19 was higher in the blood of patients with atherosclerosis, suggesting that H19 may be involved in atherosclerosis progression." (PMID 34179148, 2021). "Current research reports have illustrated that lncRNA H19 has a vital function in various cancers and CVDs; however, there is limited knowledge about its functions in the progression as well as the instability of atherosclerosis." (PMID 34820432, 2021). "Pan finds the elevated expression of lncRNA H19 in patients with atherosclerosis, and it may aggravate the damage of atherosclerosis by managing the ability of proliferation and apoptosis." (PMID 34414854, 2021). "H19 expression has been reported to be up-regulated in patients with atherosclerosis and may be a potential therapeutic target for atherosclerosis." (PMID 34421622, 2021). "However, the knockdown of lncRNA H19 served as a protection against atherosclerosis in apoE−/− mice and lowered the accumulation of lipids in ox-LDL-induced THP-1 macrophages." (PMID 34820432, 2021). "Therefore, the prevention of ANGPTL4-mediated lipid accumulation is an important mechanism by which lncRNA H19 facilitates lipid accumulation and aggravates atherosclerosis." (PMID 34820432, 2021). "Importantly, the knockdown of lncRNA H19 has been demonstrated to alleviate atherosclerosis; however, the overexpression of lncRNA H19 contributed to the progression of atherosclerosis and induced ischemic stroke." (PMID 34820432, 2021). "To determine whether lncRNA H19 expression was changed during atherosclerosis, we initially analyzed its expression in the whole blood and aortic tissues of apoE−/− mice using qRT-PCR and RNA-FISH." (PMID 34820432, 2021). "Recent studies have shown that H19 might play a critical role in the onset and progression of atherosclerosis." (PMID 33541284, 2021). "Consistent with our findings, contemporary research reports have demonstrated that lncRNA H19 was upregulated in the blood sample of atherosclerosis patients, suggesting that lncRNA H19 is a potential biomarker and prognostic indicator for atherosclerotic disease." (PMID 34820432, 2021). "H19 expression might promote it because H19 expression contributes to the development of atherosclerosis." (PMID 34220553, 2021). "However, the role of H19 in regulating cellular senescence of vascular endothelium is unclear in atherosclerosis." (PMID 34220553, 2021). "The expression of H19 was up-regulated in patients with atherosclerosis." (PMID 33381452, 2020).
atherosclerosis (continued). "Interestingly, even though its expression was only retained in a few adult tissues, H19 was found to be involved in the dysregulation of ECs during atherosclerosis." (PMID 32241300, 2020). "H19 also regulates the pathogenesis of osteoarthritis, myositis, and atherosclerosis." (PMID 32272875, 2020). "Accumulating evidences indicate that H19 participates in a variety of inflammatory-related diseases including osteoarthritis, primary sclerosing cholangitis, atherosclerosis, ischemic neuroinflammation and ulcerative colitis." (PMID 30984483, 2019). "Furthermore, H19 was found to be upregulated in atherosclerosis and to increase the levels of H19 in VSMC (vascular smooth muscle cells) and HUVSC (human umbilical vein endothelial cells), resulting in cellular proliferation and the suppression of apoptosis." (PMID 30669611, 2019). "Elevated level of lncRNA H19 was detected in the blood of the patients with coronary artery disease patients, suggesting that H19 may be involved with atherosclerosis process and a new biomarker for the diagnosis of coronary artery disease." (PMID 30778327, 2019). "Therefore, Venn diagram analysis was subsequently performed to identify the correlation between H19 target genes and atherosclerosis-related genes." (PMID 30778327, 2019). "H19 may be used as the target for the therapy of atherosclerosis by regulating WNT/beta-catenin signaling pathway in vascular smooth muscle cells." (PMID 30778327, 2019). "High levels of H19 have been found in serum patients with atherosclerosis, indeed, in mouse vascular smooth muscle cells, upon up-regulation of H19, low level of caspase 3 has been found while proliferation is improved probably due to the activation of MAP-ERK pathway linked to inflammation." (PMID 31191327, 2019). "LncRNA H19 has been reported to be overexpressed in atherosclerotic patients, and may be a potential target in the prevention of atherosclerosis." (PMID 30778327, 2019). "Critical evidence based on examination of human atherosclerosis specimens suggested that H19 was predominantly expressed in the endothelial cell, where its expression was significantly down-regulated in pathological samples compared with healthy carotid artery biopsies." (PMID 31757932, 2019). "Moreover, opposite results were found in the aortic tissues of atherosclerosis mice treated with H19 or CTCF overexpression." (PMID 31757932, 2019). "Moreover, H19 was shown to be elevated in serum of patients with atherosclerosis as well as in atherosclerotic plaques of ApoE-knockout mice treated with high-fat diet." (PMID 30013975, 2018). "A recent study showed that over-expression of H19 could promote atherosclerosis by activating MAPK and NF-κB signaling pathway." (PMID 28790415, 2017). "Since ApoE(−/−) mice spontaneously exhibit atherosclerosis despite the diet, the results indicated that the high levels of H19 expression found in these mice might contributed to the spontaneous development of atherosclerosis." (PMID 27698357, 2016). "All these research indicated that H19 is related to atherosclerosis." (PMID 27698357, 2016). "Moreover, the H19 that was upregulated by m6A modification was likely to aggravate atherosclerosis." (PMID 39432244, 2024). "Thus, H19 could link lipid accumulation and inflammation, and knockdown of H19 might be a therapeutic strategy in atherosclerosis." (PMID 32082313, 2020).
atherosclerosis (continued). "H19 is downregulated in insulin‐resistant skeletal muscle and its restoration improves insulin signaling; conversely, in vascular cells H19 upregulation has been linked to neointima formation and atherosclerosis, indicating tissue‐dependent effects rather than atherogenesis driven by H19 deficiency." (PMID 41567175, 2026). "Deregulation of lncRNAs, including H19, TUG1, GAS5, RAPIA, MIAT, CASC11, NEXN-AS1, and lnc00113, has been observed in individuals with atherosclerosis." (PMID 40941416, 2025). "Other lncRNAs involved in MI pathology: H19 regulates VSMC proliferation and apoptosis by acting as a ceRNA for miR-138 and miR-200a, influencing cell growth and apoptosis in atherosclerosis." (PMID 39135912, 2024). "Collectively, this study has revealed the little‐known mechanism of m6A participating in atherosclerosis by regulating lncRNA expression and demonstrated that targeted inhibition of METTL3 and H19 is a potential treatment strategy for atherosclerosis." (PMID 39432244, 2024). "The deregulation of many lncRNAs, including RAPIA, H19, CASC11, GAS5, TUG1, MIAT, lnc00113, and NEXN-AS1, has been observed in patients with atherosclerosis." (PMID 39273193, 2024). "For example, lncRNA H19 can target certain RNAs to regulate MAPK signal pathways and promote the development of atherosclerosis and arterial calcification." (PMID 35890121, 2022). "Previous studies on atherosclerosis have shown that there are a variety of lncRNAs, including MALAT1, H19, ATB, LEF1-AS1, and ZEB1-AS1, which are promising therapeutic targets." (PMID 35028010, 2022). "lncRNA H19 promoted the expression of ANGPTL4 via competitively binding to miR-146a-5p, thus promoting lipid accumulation in atherosclerosis." (PMID 34820432, 2021). "The present study provides evidence that H19 recruits CTCF to downregulate the expression of PKD1, thereby promoting vulnerable plaque formation and intraplaque angiogenesis in mice with atherosclerosis." (PMID 31757932, 2019). "H19 was capable of recruiting CTCF to suppress PKD1, thus promoting atherosclerotic vulnerable plaque formation and intraplaque angiogenesis in atherosclerosis mice." (PMID 31757932, 2019). "Thirdly, further experimental studies using animal or cellular model are needed to explore the mechanisms by which H19 and LIPCAR participate in the development of atherosclerosis." (PMID 28790415, 2017). "To clarify whether H19 was involved in the process of METTL3 aggravating atherosclerosis, we first consulted the SRAMP database and learned that H19 had as many as 41 potential m6A modification sites." (PMID 39432244, 2024). "Thus, our research offers novel acumens into the molecular role of lncRNA H19/miR-146a-5p/ANGPTL4 signaling pathway in lipid accumulation and highlights lncRNA H19 as a promising therapeutic target for atherosclerosis." (PMID 34820432, 2021). "The expression of H19 and RAPIA has been found to be increased in patients with atherosclerosis." (PMID 35011565, 2021). "Furthermore, lncRNA H19 served as a microRNA (miRNA) sponge in the positive regulation of the ANGPTL4 expression by sponging miR-146a-5p, thereby promoting lipid accumulation in atherosclerosis." (PMID 34820432, 2021). "This study aimed to explore the interactions among long non-coding RNA H19, transcriptional factor CCCTC-binding factor (CTCF) and polycystic kidney disease 1 (PKD1), and to investigate its potentially regulatory effect on vulnerable plaque formation and angiogenesis of atherosclerosis." (PMID 31757932, 2019). "The data suggested that H19 may regulate MAPK and NF-kB in atherosclerosis." (PMID 30013975, 2018). "With “atherosclerosis” as the key word retrieved in NONCODE, H19, ANRIL, and CDKN2B-AS1 were found to be involved in atherosclerosis onset." (PMID 30778327, 2019).